ZNF600 (zinc finger protein 600)
Description:
May be involved in transcriptional regulation.
Synonyms: KR-ZNF1; DKFZp686F06123
Tractability: PROTAC: ubiquitination databases record sites on it.
Gene: Protein-coding gene on chromosome 19 (52,749,942 to 52,786,820, reverse strand). Ensembl gene ENSG00000189190.
Subcellular location: Nucleus
Pathways (Reactome):
Gene expression (Transcription): Generic Transcription Pathway
Gene Ontology:
Molecular function: protein binding; transcription cis-regulatory region binding
Biological process: negative regulation of transcription by RNA polymerase II; regulation of gene expression
Cellular component: nucleus
Genetic constraint (gnomAD): Loss-of-function variants: 4 observed, 8.81 expected, observed/expected ratio (o/e) 0.45, 90% interval 0.22 to 1.04. That is too few expected variants to judge how well the gene tolerates losing a copy. Missense variants: 911 observed, 953.64 expected, observed/expected ratio (o/e) 0.96, 90% interval 0.9 to 1.01. Synonymous variants: 290 observed, 321.14 expected, observed/expected ratio (o/e) 0.9, 90% interval 0.82 to 1.
Homologues: Orthologues: chimpanzee ZNF600 (90% identical), macaque ZNF600 (86% identical). Paralogues in human: ZNF611 (79% identical), ZNF28 (40% identical), ZNF534 (40% identical), ZNF595 (39% identical), ZNF320 (37% identical), ZNF726 (37% identical), ZNF836 (36% identical), ZNF724 (36% identical), ZNF85 (36% identical), ZNF33B (36% identical), ZNF658 (36% identical), ZNF708 (36% identical), and 164 more.
Diseases named in the same sentence as ZNF600 in open-access papers:
ZNF600 is named in the same sentence as 1 disease in open-access papers, as found by Europe PMC text mining. Sharing a sentence is not in itself a finding about the gene and the disease. The quoted sentences say what the papers report.
tumor (1 paper, 2014). "Conversely, in normal kidney tissue PPWD1, LUMCH1 and ZNF600 were down regulated in smokers compared to non-smokers; however, these genes were up regulated in smokers versus non-smokers in ccRCC tumor tissue." (PMID 24479813, 2014).